HMGB1 (high mobility group box 1)
Diseases named in the same sentence as HMGB1 in open-access papers (continued):
Sharing a sentence is not in itself a finding about the gene and the disease.
asthma (continued). "Despite these advancements, there remain significant gaps in our understanding, particularly regarding the role of less conventional alarmins like HMGB1, IL-1α, IL-36 and TL1A in asthma pathology, as well as genetic factors that predispose patients to respond to specific biologics." (PMID 39457624, 2024). "In addition, inhibition of HMGB1 protects human bronchial epithelial cells (HBE) by alleviating TDI‐induced asthma via ROS/AMPK/autophagy pathway." (PMID 38156383, 2023). "The abnormal structure, expression, and activation of HMGB1 may mediate inflammatory response to affect the occurrence and development of asthma." (PMID 38156383, 2023). "Anti-HMGB1 mitigates both early-life viral disease and later-life asthma-like features." (PMID 37798799, 2023). "The levels of HMGB1 in the sputum of subjects with severe asthma and of the RAGE and HMGB1 produced by the nasal cells of subjects with chronic rhinosinusitis with nasal polyposis (CRSwNP) and eosinophilic inflammation are higher than in patients with mild disease." (PMID 36675299, 2023). "Increasing studies have shown that HMGB1 plays a role in different acute and chronic airway inflammation and plays an important role in the occurrence and development of respiratory diseases such as asthma." (PMID 38156383, 2023). "HMGB1 is involved in the occurrence of many diseases and plays an important role in asthma." (PMID 38156383, 2023). "Accordingly, HMGB1 emerges as a therapeutic target for asthma." (PMID 38156383, 2023). "Moreover, patients with severe asthma showed higher levels of sputum HMGB1 than patients with mild and moderate asthma." (PMID 36830972, 2023). "IL-33 and HMGB1 have a significant role in Th2 inflammation and severe asthma." (PMID 36675299, 2023). "Increasing the stability of HMGB1 promotes autophagy induced by oxidative stress to improve asthma." (PMID 38156383, 2023). "In addition, HMGB1 is the substrate of RNF125 which is downregulated in the bronchial epithelium of asthma patients." (PMID 38156383, 2023). "This article reviews the role and mechanism of HMGB1 in asthma." (PMID 38156383, 2023). "Epithelial miR-30a-3p could possibly target RUNX2/HMGB1 axis to suppress airway eosinophilia in asthma." (PMID 35093061, 2022). "In addition, we found that miR-30a-3p transcripts levels negatively correlated with HMGB1 transcripts in bronchial brushings from asthma patients." (PMID 35093061, 2022). "We conclude that epithelial miR-30a-3p could possibly target RUNX2/HMGB1 axis to suppress airway eosinophilic inflammation in asthma." (PMID 35093061, 2022). "S100A8/A9 and HMGB-1 might be involved in the pathobiology of remodeling in asthma by promoting inflammation and tissue repair in the airway." (PMID 35626330, 2022). "HMGB1 plays a key role in the pathogenesis of airway inflammation in asthma." (PMID 35093061, 2022). "Moreover, epithelial RUNX2 transcript levels in bronchial brushings were positively correlated with HMGB1 transcript levels in asthma patients." (PMID 35093061, 2022). "Additionally, animal models of asthma showed that ovalbumin induced the expression of HMGB1, TLR2, and TLR4 in the lung, while inhibiting HMGB1 reduced the number of Th1, Th2, and Th17 cells to dampen airway inflammation." (PMID 33140586, 2021). "In the HDM-induced asthma model, immunochemistry findings showed that HMGB1 was mainly expressed in airway epithelium and some peripherally infiltrative lymphocytes of lung tissues, suggesting that airway epithelial cell was an important source of HMGB1 production." (PMID 33541260, 2021). "HMGB1 was shown to strongly stimulate the differentiation of Th cells and innate lymphocytes (e.g., DCs, group 2 innate lymphoid cells (ILC2s)) and contribute to asthma." (PMID 33925132, 2021). "Levels of HMGB1 in the airway are elevated in animal models and patients with asthma." (PMID 33925132, 2021). "HMGB1 activated ILC2s and DCs in a mouse model of asthma, exacerbating the disease." (PMID 33925132, 2021).
asthma (continued). "Similarly, HMGB1 promotes IL-9 release to activate group 2 innate lymphoid cells and DCs, aggravating asthma." (PMID 33925132, 2021). "As we had previously shown that RAGE-/- mice generate attenuated type-2 inflammatory responses to both viral- or allergen-triggered experimental asthma, we speculated that HMGB1/RAGE ligation promotes type-2 cytokine production by ILC2s." (PMID 32658914, 2020). "In summary, therapeutic targeting of the HMGB1/RAGE signalling axis may act as a novel asthma preventative by dampening ILC2-mediated type-2 inflammation and associated ASM remodelling." (PMID 32658914, 2020). "Of note, ASM expression of HMGB1 is elevated in lung biopsies of patients with asthma." (PMID 32658914, 2020). "Sputum HMGB1 values were positively related to total IgE levels in children with asthma." (PMID 28630596, 2017). "Severe asthma subjects had higher sputum levels of HMGB-1 than moderate and mild patients." (PMID 28630596, 2017). "Thus, the specific role of disulphide HMGB1 in the development of asthma represents an area of ongoing investigation." (PMID 28099113, 2017). "Our study indicated that HMGB1, a late-phase cytokine, might be a potential therapeutic target for treatment of severe cases of asthma and COPD in the future." (PMID 26739898, 2016). "Moreover, patients with COPD showed a higher concentrations of sputum HMGB1 than patients with all severities of asthma." (PMID 26798204, 2015). "According to these findings and hypothesis, another study evaluated sputum and plasma concentrations of HMGB1 in patients affected by asthma and COPD." (PMID 26798204, 2015). "We hypothesize that HMGB1 directs Th17 skewing by regulating DC function, and HMGB1 blocking inhibits the Th17 response and Th17-mediated neutrophilic airway inflammation in asthma." (PMID 24959003, 2014). "However, the Penh was significantly reduced in anti-HMGB1 IgG-treated mice compared with asthma group animals (P < 0.05)." (PMID 24959003, 2014). "To demonstrate the important role of HMGB1 signaling in DC-primed allergic disease, we also investigated whether adoptive transfer of HMGB1-activated DCs was sufficient to restore neutrophilic inflammation and the Th17 response in a DC-driven model of asthma." (PMID 24959003, 2014). "The precise mechanism through which HMGB1 induces EMT in asthma remains unclear, but it may potentially involve RAGE and the phosphatidylinositol 3′ -kinase/Akt/glycogen synthase kinase 3β/β-catenin (PI3K/Akt/GSK3β/β-catenin) signaling pathway or the RAGE/NF-κB signaling pathway." (PMID 38562155, 2024). "In addition, the main signaling pathway of HMGB1 involved in asthma is HMGB1/TLR4/NF‐κB and HMGB1/RAGE, while whether the JAK/STAT signaling pathway is involved in HMGB1 still unclear at present." (PMID 38156383, 2023). "For example, HMGB1/RAGE signaling synergically enhances TGF‐β1‐induced broncho‐airway remodeling and epithelial‐mesenchymal transformation (EMT) by promoting Th17 cell differentiation and IL‐17 secretion, which is one of the causes of severe steroid‐resistant asthma." (PMID 38156383, 2023). "Therefore, epithelial miRNA-30a-3p could target the RUNX2/HMGB1 axis to reduce airway eosinophilia in asthma." (PMID 36675299, 2023). "This means that HMGB1 may be a potential biomarker of asthma severity." (PMID 38156383, 2023). "Besides, high mobility group box 1 (HMGB1) secreted by some injury cells or immune cells in asthma could promote the activation of TLR4, inhibited by heat shock factor 1 (HSF1), when bound with HMGB1 promotor." (PMID 36582191, 2022). "Inhaled glucocorticoid therapy could reduce sputum HMGB1 levels in moderate to severe asthma." (PMID 33140586, 2021). "However, whether RAGE or HMGB1 contribute to viral bronchiolitis in early life, and the subsequent development of viral-induced asthma, remains to be determined." (PMID 28099113, 2017).
asthma (continued). "Therefore, antagonists of HMGB1 might be promising therapeutic molecules that could treat severe asthma characterized by dominant Th17 phenotypes." (PMID 24959003, 2014). "Finally, we show that intranasal adoptive transfer of rHMGB1-activated DCs was sufficient to restore lung neutrophilic inflammation and the Th17 response in a DC-driven model of asthma, whereas the transfer of rHMGB1 plus anti-HMGB1-treated mDCs significantly reduced these inflammation phenotypes." (PMID 24959003, 2014). "Therefore, HMGB1 could serve as a biomarker of asthma severity." (PMID 40723867, 2025). "In a different model, reducing the binding of HMGB1 to RAGE was shown to alleviate T regulatory (Treg)/Th17 immune imbalance, and block allergic rhinitis from developing into asthma." (PMID 39766257, 2024). "HMGB1/TLR4/NF‐κB, HMGB1/RAGE, JAK/STAT, and HMGB1/TGF‐β play important roles in the occurrence and development of asthma." (PMID 38156383, 2023). "In a mouse model of asthma, the overexpression of miR-30a-3p suppressed RUNX2 and HMGB1 and decreased eosinophilic inflammation." (PMID 36675299, 2023). "Our study suggests a mechanism by which evodiamine hinders the development of asthma in rats by altering expression of TLR-4, NF-κB, MyD88, and HMGB1, thus hindering airway remodelling in the rat lung." (PMID 33577738, 2021). "This study determines a relationship between CC16 and HMGB1 signaling in HDM-induced asthma, indicating that CC16 seems to be a potent protector of airway epithelium dysfunction via negatively regulating HMGB1 signaling." (PMID 33541260, 2021). "Our data confirm that CC16 attenuates HDM-mediated airway inflammation and damage via suppressing airway epithelial cell apoptosis in a HMGB1-dependent manner, suggesting the role of CC16 as a potential protective option for HDM-induced asthma." (PMID 33541260, 2021). "In experimental asthma, lipoxins regulate NK or ILC2 activation, and in experimental psoriasis model induced by imiquimod, they reduce IL-17A and IL-22 production via HMGB1 modulation." (PMID 32161582, 2020). "IL-33 is thought to be the main driver of ILC2 expansion and activation, however a growing body of evidence is beginning to implicate high-mobility group box 1 (HMGB1), another nuclear alarmin whose extracellular expression correlates with asthma severity." (PMID 32658914, 2020). "The levels of HMGB1 and Gal-3 proteins in ACO patients were elevated compared to those in asthma patients." (PMID 31848359, 2019). "Increased levels of several DAMPs, including HMGB1, HSPs, and S100A8, have been observed in induced sputum and serum of asthma and COPD patients in our and other previous studies that are implicated in the pathogenesis of asthma and COPD." (PMID 31848359, 2019). "Sputum HMGB1 displayed a high AUC of the ROC curve that distinguished ACO patients from NS, HS, and asthma patients." (PMID 31848359, 2019). "Sputum from subjects with asthma (n = 87) or COPD (n = 73) and ACO (n = 68) or from smokers (n = 62) and never-smokers (n = 62) was analyzed for high mobility group protein B1 (HMGB1), heat shock protein 70 (HSP70), LL-37, S100A8, and galectin-3 (Gal-3)." (PMID 31848359, 2019). "Strikingly, the current study stated that sputum HMGB1 had a high sensitivity and specificity in distinguishing ACO from NS, HS, and asthma patients and in distinguishing asthmatics from COPD." (PMID 31848359, 2019). "To further explore the mechanism underlying the Th17 skewing effects of HMGB1, we focused on pulmonary DCs, which play a major role in the pathogenesis of asthma and preferentially express RAGE, which is a receptor for HMGB1." (PMID 24959003, 2014). "Another recent study demonstrated positive correlations between the levels of HMGB1 or RAGE and the percentage of neutrophils in asthma patients." (PMID 24102034, 2013).
asthma (continued). "Interestingly, high-mobility group box-1 (HMGB1) protein, which is expressed by club cells in the lung, promotes airway hyperresponsiveness and an asthma-like type 2 response." (PMID 40021627, 2025). "Serum concentrations of p-MLKL and RIPK3 were significantly elevated in asthma patients compared to healthy controls, but no significant change in the level of HMGB1 was observed (data not shown)." (PMID 38987753, 2024). "Interestingly, the expression of miR-181a in the lung of allergic rhinitis mice reduced the count of eosinophils in BALF and decreased IL-4, IL-5, and IL-13 by targeting high mobility group box 1 (HMGB1), resulting in retarded development of asthma." (PMID 38337625, 2024). "Levels of HMGB1 in the induced sputum of patients with COPD were significantly higher than those of patients with asthma and healthy controls not reporting significant differences in HMGB1 levels between patients with eosinophilic and non-eosinophilic asthma." (PMID 36830972, 2023). "Accordingly, both HMGB1/NF‐κB and HMGB1/TLR4 signals may be involved in the occurrence and development of asthma." (PMID 38156383, 2023). "In a mouse model, blocking HMGB-1 and TLR-4 attenuated disonoyl phthalate-induced asthma." (PMID 35626330, 2022). "TUG1, serving as the molecular sponge of miR-138-5p, miR-590-5p, miR-216a-3p, and miR-181b, has been confirmed to be involved in ASMC proliferation and migration in human asthma by modulating E2F transcription factor 3 (E2F3), fibroblast growth factor 1 (FGF1), Smurf2 and HMGB1, respectively." (PMID 35769905, 2022). "Thus, our data suggest that by dampening type-2 inflammation and attenuating virus-associated ASM remodelling, biologics or small molecules targeting HMGB1 and/or RAGE will serve as novel preventatives for the treatment of asthma." (PMID 32658914, 2020). "Likewise, the level of several RAGE ligand such as advanced glycation end products (AGE), HMGB1 and S100 family are increased in COPD and asthma patients and correlate with disease airflow limitation severity and negatively associated with FEV1%." (PMID 30013476, 2018). "In 2011 they dosed HMGB-1 and esRAGE levels in induced sputum of 44 asthmatic patients (before any asthma treatment) and 15 normal controls (Japanese, non-smokers subjects, with no history of respiratory infection for minimum of 4 weeks before the study)." (PMID 28630596, 2017). "There were no significant variation in sputum HMGB1 levels between subjects with mild asthma and controls and between mild asthma and moderate asthma." (PMID 28630596, 2017). "The expression of HMGB1 and TLR4 mRNAs in 1,25-(OH)2D3 low and middle dose groups was considerably lower than the asthma group and higher than the control one; the high dose group had an augmented expression of HMGB1 and TLR4 mRNAs compared to the asthmatic group." (PMID 28630596, 2017). "Importantly, the lower HMGB1 concentrations used in our study reflect the circulatory levels observed in IPAH, asthma and COPD patients as measured by us and others 4,5." (PMID 25726846, 2015). "Thus in looking for potential etiology factors of CRSwNP, we assessed allergy, AERD, asthma and microbiologic status of nasal cavity for their correlation with RAGE and HMGB1." (PMID 25503556, 2015). "This work distinguished P2Y13-R as a new gatekeeper of the nuclear alarmins IL-33 and HMGB1 and recognized that targeting this GPCR via genetic deletion or therapy with a small-molecule antagonist defended against the onset and exacerbation of experimental asthma." (PMID 36675299, 2023). "Therefore, in this paper we aim to analyze the role of alarmins, in particular of HMGB1 and TSLP, in asthma and COPD, identifying similarities and differences which may be useful for therapeutic approaches that are as targeted as possible." (PMID 36830972, 2023).
asthma (continued). "Besides, emerging studies revealed that HMGB1 was elevated in induced sputum and plasma in asthmatic patients, and that measures to inhibit HMGB1 were helpful to alleviate airway inflammation in ovalbumin(OVA)-induced asthma model." (PMID 33541260, 2021). "Importantly, sputum HMGB1 is a novel biomarker for differentiating ACO from healthy controls, and sputum LL-37 may also serve as a valuable biomarker for differentiating asthma and COPD." (PMID 31848359, 2019). "The release of sputum DAMPs in ACO may be involved in chronic airway inflammation in ACO; the sputum HMGB1 level might serve as a valuable biomarker for distinguishing ACO from asthma, and the sputum LL-37 level might be a biomarker for differentiating asthma and COPD." (PMID 31848359, 2019). "Moreover, sputum HMGB1 may serve as a biomarker for the differentiation of ACO patients from NS, HS, and asthma patients, while sputum LL-37 may differentiate asthmatics from those with COPD." (PMID 31848359, 2019). "In light of the fact that TLR4 was essential for ASM growth and the cardinal features of asthma in this model, it is tempting to speculate that disulphide HMGB1/TLR4 interactions are sufficient to induce early life airway remodelling and the development of asthma later in life." (PMID 28099113, 2017). "The mechanism of airway hyperreactivity and remodelling in these patients remains unclear, and indeed HMGB1 levels, although known to be elevated in eosinophilic asthma have never been thoroughly investigated in in paucigranulocytic asthma." (PMID 28099113, 2017). "Hence, the authors have suggested that both HMGB1 and RAGE may play a role in inflammatory process and pathogenesis of asthma." (PMID 24102034, 2013). "Moreover, HMGB1 may be involved in the pathogenesis of asthma by regulating downstream signaling pathways through corresponding receptors and mediates a number of signaling pathways in asthma, such as HMGB1/TLR4/NF‐κB, HMGB1/RAGE, HMGB1/TGF‐β, and so forth." (PMID 38156383, 2023).